KLHL36 (kelch like family member 36)
Description:
Probable substrate-specific adapter of an E3 ubiquitin-protein ligase complex which mediates the ubiquitination and subsequent proteasomal degradation of target proteins.
Synonyms: C16orf44; FLJ12543
Tractability: Small molecule: it belongs to a druggable protein family. PROTAC: ubiquitination databases record sites on it; its protein half-life has been measured.
Gene: Protein-coding gene on chromosome 16 (84,643,425 to 84,667,837, forward strand). Ensembl gene ENSG00000135686.
Subcellular location (Human Protein Atlas): Cytosol
Gene Ontology:
Molecular function: cullin family protein binding; protein binding; ubiquitin-like ligase-substrate adaptor activity
Biological process: proteasome-mediated ubiquitin-dependent protein catabolic process; protein ubiquitination
Cellular component: Cul3-RING ubiquitin ligase complex
Genetic constraint (gnomAD): Loss-of-function variants: 31 observed, 45.52 expected, observed/expected ratio (o/e) 0.68, 90% interval 0.51 to 0.92. The synonymous counts are far from expectation, so gnomAD's model fits this gene poorly and the ratio says little. Missense variants: 848 observed, 863.23 expected, observed/expected ratio (o/e) 0.98, 90% interval 0.93 to 1.04. Synonymous variants: 468 observed, 390.62 expected, observed/expected ratio (o/e) 1.2, 90% interval 1.11 to 1.29.
Homologues: Orthologues: chimpanzee KLHL36 (99% identical), dog KLHL36 (97% identical), pig KLHL36 (95% identical), guinea pig KLHL36 (89% identical), rabbit KLHL36 (89% identical), rat Klhl36 (86% identical), mouse Klhl36 (86% identical), tropical clawed frog klhl36 (77% identical), zebrafish klhl36 (62% identical). Paralogues in human: KLHL9 (34% identical), KLHL13 (34% identical), KLHL26 (32% identical), KLHL32 (31% identical), KLHL22 (30% identical), KLHL14 (29% identical), KLHL31 (28% identical), KLHL34 (28% identical), KLHL2 (27% identical), KLHL5 (27% identical), KLHL20 (26% identical), KLHL3 (26% identical), and 42 more.
Diseases named in the same sentence as KLHL36 in open-access papers:
KLHL36 is named in the same sentence as 9 diseases in open-access papers, as found by Europe PMC text mining. Sharing a sentence is not in itself a finding about the gene and the disease. The quoted sentences say what the papers report.
Alzheimer disease (1 paper, 2022). A progressive, neurodegenerative disease characterized by loss of function and death of nerve cells in several areas of the brain leading to loss of cognitive function such as memory and language. "The SNP in KLHL36 (Kelch Like Family Member 36) also had a significant association with self-reported resilience, and this variant has previously been discovered as a risk variant for late onset Alzheimer’s Disease." (PMID 35599764, 2022).
depression (1 paper, 2025). "While loss of SLC6A15 function was reported to be associated with depression, increased KLHL36 expression has been tentatively correlated with suicide attempts." (PMID 40355756, 2025).
glaucoma (1 paper, 2017). Increased pressure in the eyeball due to obstruction of the outflow of aqueous humor. "Three genes, SRBD1, CLIC5, and KLHL36, have been found to be involved in immune responses and reported to be associated with various phenotypes, such as glaucoma, neurological disorders, and carcinoma." (PMID 28355295, 2017).
skin fragility (1 paper, 2021). "Further, KLHL36 is part of the E3 ubiquitin ligase family which has been implicated in skin fragility and fibroblast pseudopodia function —again highlighting the potential role of this gene in fibroblast biology and physiology." (PMID 33673841, 2021).
cancer (2 papers, 2017 to 2018). A tumor composed of atypical neoplastic, often pleomorphic cells that invade other tissues. "KLHLs with significant hazard ratios or inverse hazard ratios for four cancer types regardless of direction were KLHL14, KLHL22, KLHL29, KLHL32, and KLHL36." (PMID 30647843, 2018).
KLHL36 also shares sentences with these, for which no sentence is quoted: autism (1 paper); neurological disorders (1); psychiatric disorder (1); schizophrenia (1).